LIM2 (lens intrinsic membrane protein 2)
Description:
Present in the thicker 16-17 nm junctions of mammalian lens fiber cells, where it may contribute to cell junctional organization. Acts as a receptor for calmodulin. May play an important role in both lens development and cataractogenesis.
Synonyms: MP19; MP17; CTRCT19
Tractability: Antibody: UniProt predicts a signal peptide or a membrane-spanning region; its Gene Ontology location is reachable by antibodies, with medium confidence.
Gene: Protein-coding gene on chromosome 19 (51,379,909 to 51,388,264, reverse strand). Ensembl gene ENSG00000105370.
Subcellular location: Membrane
Gene Ontology:
Molecular function: structural constituent of eye lens
Biological process: cell-cell junction assembly
Cellular component: cell junction; plasma membrane; membrane; vesicle
Genetic constraint (gnomAD): Loss-of-function variants: 14 observed, 20.28 expected, observed/expected ratio (o/e) 0.69, 90% interval 0.46 to 1.08. The upper end of that interval is the gene's LOEUF score, 1.08, which puts it in group 4 of 6, group 1 being the genes least tolerant of losing a copy. Missense variants: 230 observed, 254.7 expected, observed/expected ratio (o/e) 0.9, 90% interval 0.81 to 1.01. Synonymous variants: 78 observed, 95.32 expected, observed/expected ratio (o/e) 0.82, 90% interval 0.68 to 0.99.
Homologues: Orthologues: chimpanzee LIM2 (99% identical), macaque LIM2 (97% identical), rat Lim2 (92% identical), dog LIM2 (91% identical), mouse Lim2 (91% identical), pig LIM2 (91% identical), guinea pig LIM2 (90% identical), tropical clawed frog lim2 (79% identical), zebrafish lim2.5 (79% identical), zebrafish lim2.4 (75% identical). Paralogues in human: CLDND2 (27% identical), PMP22 (24% identical), EMP2 (23% identical), GSG1L (22% identical), NKG7 (22% identical), GSG1L2 (21% identical), EMP1 (21% identical), GSG1 (20% identical), TMEM202 (20% identical), EMP3 (18% identical).
Diseases named in the same sentence as LIM2 in open-access papers:
LIM2 is named in the same sentence as 15 diseases in open-access papers, as found by Europe PMC text mining. Sharing a sentence is not in itself a finding about the gene and the disease. The quoted sentences say what the papers report.
cataract (12 papers, 2008 to 2022). Partial or complete opacity of the crystalline lens of one or both eyes that decreases visual acuity and eventually results in blindness. "Here, we report a novel missense mutation in LIM2 that segregates with autosomal recessive congenital cataracts in a consanguineous Pakistani family." (PMID 27814360, 2016). "Previously, only two causal mutations in LIM2 have been identified in patients with cataracts; the mutation identified here is now a third avenue of insight into the role of LIM2 in cataractogenesis." (PMID 27814360, 2016). "In contrast, loss-of-function mechanisms in Lim2-deficient mice induced only faint central cataracts in a recessive manner." (PMID 21617753, 2011). "The semidominant pattern of the To3 mutation highlights the genetic complexity of LIM2 in the formulation of cataracts." (PMID 21386927, 2011). "A novel missense mutation in LIM2 is responsible for autosomal recessive congenital cataracts." (PMID 27814360, 2016). "Although the role of the four studied genes: PAX6, PITX3, HSF4 and LIM2 in both ocular and central nervous system development, we report the absence of mutations in all studied genes in four families with phenotypes associating cataract, MR and microcephaly." (PMID 22103961, 2011). "Additionally, Hsf4, Tdrd7, gap junction protein epsilon 1 (Gje1), beaded filament structural protein 2 (Bfsp2), and lens intrinsic membrane protein 2 (Lim2) which are also significantly reduced in the SCR lens (<0.5-fold) were linked to human or animal cataracts (Supplement 1)." (PMID 33204712, 2020). "Recently, we described two mouse mutants which have been identified by their smaller eyes in heterozygotes, but later in life or as homozygous mutants they developed cataracts; the affected genes are Cryba2 and Lim2 (lens intrinsic membrane protein 2)." (PMID 25951169, 2015). "A dominant negative effect of the To3 mutation was also suggested in studies on the Lim2 To3 transgenic mice, which demonstrated severe cataracts despite the amount of transgenic Lim2 mRNA present being much lower than wild type Lim2 mRNA." (PMID 18596884, 2008). "In contrast, mice lacking Lim2 exhibited only faint, central pulverulent cataracts." (PMID 21617753, 2011).
congenital cataracts (5 papers, 2008 to 2016). "In conclusion, we report a missense mutation in the sequence of LIM2 encoding the second transmembrane domain of MP19 that causes autosomal recessive congenital cataracts." (PMID 27814360, 2016). "Lim2 encodes a lens specific protein probably involved in cell junctions, and mutations in humans are associated with congenital cataracts." (PMID 21896182, 2011). "Mutations in LIM2 were related to autosomal recessive congenital cataracts in humans." (PMID 21386927, 2011). "The findings of this study support the possibility that additional cases of human congenital cataracts might be initiated by yet unknown LIM2 mutations." (PMID 21617753, 2011).
Age-related cataract (2 papers, 2011 to 2023). A type of cataract (opacification of the lens) that forms during the course of aging. "The genetic mutation in GJA3, GJA8, and LIM2 may slightly contribute to the development of age-related cataracts." (PMID 21386927, 2011). "A study found a potential relationship between old age and the LIM2 gene, as it is involved in the development of age-related cataracts." (PMID 36674212, 2023).
Age-related nuclear cataract (1 paper, 2024). A type of age-related cataract that primarily affects the nucleus of the lens. "Variants in many genes underlying inherited forms of cataract (e.g., BFSP1, LIM2, MIP, and CHMP4B) have been shown to exhibit tentative association with age-related nuclear cataract." (PMID 38927721, 2024).
brain tumors (1 paper, 2017). "We went on to further investigate the prognostic significance of LIM2, and found that a low level of LIM2 was significantly correlated with a shorter survival time in patients with brain tumors (p = 0.005)." (PMID 28055976, 2017). "Importantly, CD133 expression and LIM2 expression were independent prognostic markers in brain tumor patients as shown by multivariate Cox regression analysis." (PMID 28055976, 2017).
cortical cataract (1 paper, 2011). A cataract (disease) that involves the lens cortex. "In LIM2, a 56-year-old women with cortical cataracts was found to carry a heterozygous sequence alteration c.67A>C that leads to p.M23L; meanwhile, another 62-year-old woman carried a heterozygous synonymous mutation c.57G>A." (PMID 21386927, 2011).
glioma (1 paper, 2017). A benign or malignant brain and spinal cord tumor that arises from glial cells (astrocytes, oligodendrocytes, ependymal cells). "Furthermore, we showed that low-level expression of LIM2 in CD133-high glioma was associated with poorer survival, suggesting that LIM2 could be a therapeutic target for glioma expressing a high level of CD133." (PMID 28055976, 2017). "LIM2, lens intrinsic membrane protein 2, has been shown to maintain cytoskeletal integrity, cell morphology and intercellular communication in mouse lenses, but little was known about the role of LIM2 in cancer or in glioma." (PMID 28055976, 2017). "Further investigations are required to understand how LIM2 interacts with CD133 in glioma progression." (PMID 28055976, 2017). "We have also identified LIM2 as a factor that could further predict survival in patients with CD133-high glioma." (PMID 28055976, 2017). "Connectivity mapping identified vinblastine and vincristine as agents that could reverse the CD133/HOX genes/LIM2-signature, and we confirmed this by in vitro analysis in glioma cell lines, demonstrating that CD133 and HOX genes were co-expressed and could be downregulated by vincristine." (PMID 28055976, 2017).
mental retardation (1 paper, 2023). "In previous work, we reported the absence of mutations in four genes (PAX6, PITX3, HSF4 and LIM2 genes) encoding for congenital cataract and expressed in the human brain in Tunisian families with cataract and mental retardation." (PMID 37179318, 2023).
cancer (2 papers, 2017 to 2025). A tumor composed of atypical neoplastic, often pleomorphic cells that invade other tissues. "To verify whether the LIM4 domain of FHL3 has reproducible cancer-promoting functions, we transiently transfected LIM2, LIM3, and LIM4 deletion mutants into Hep3B cells." (PMID 41184244, 2025). "The results of the CCK-8, EdU, transwell, and scratch assays revealed that deletion of the LIM4 domain of FHL3 significantly reduced the cancer-promoting function of FHL3, whereas deletion of the LIM2 or LIM3 domain had little effect on the cancer-promoting function of FHL3." (PMID 41184244, 2025). "However, to the best of our knowledge, there seems to be no prior evidence implicating an involvement of LIM2 in cancer." (PMID 28055976, 2017).
tumor (2 papers, 2020 to 2022). "In contrast with control sinusoids, NOZ‐penetrated sinusoid wall was characterized by enlarged fenestrae of LSECs, which was even more evident in LiM2‐NOZ tumor models." (PMID 33252861, 2020).
LIM2 also shares sentences with these, for which no sentence is quoted: autosomal dominant cataract (1 paper); Charcot-Marie-Tooth disease (1); infection (1); microcephaly (1); viral infection (1).